MYC (MYC proto-oncogene, bHLH transcription factor)
Diseases named in the same sentence as MYC in open-access papers (continued):
Sharing a sentence is not in itself a finding about the gene and the disease.
osteosarcoma (continued). "In the current study we took the opposite approach - whereby metabolic changes were examined when MYC was suppressed in osteosarcoma cells highly dependent on MYC for their tumorigenic potential." (PMID 24280108, 2013). "Forced overexpression of IFI16 protein in Saos2 (a human osteosarcoma cell line) cells down-regulated the expression of c-MYC gene." (PMID 20052289, 2010). "The incidence of MYC amplification in pagetic osteosarcoma was thus significantly higher than that in primary osteosarcoma (p = 0.016).Discussion." (PMID 18521214, 1997). "Three out of five patients (60%) with pagetic osteosarcoma showed MYC gene amplification, whereas it was present in only 5/53 patients (9.4%) with primary osteosarcoma." (PMID 18521214, 1997). "Based on this observation, we further investigated the prevalence of MYC gene amplification in pagetic osteosarcomas.Methods." (PMID 18521214, 1997). "In a previous series of 25 human osteosarcoma samples studied for MYC gene amplification, we found amplification in two cases (8%), including one arising in association with Paget's disease (pagetic osteosarcoma)." (PMID 18521214, 1997). "The clinical efficacy of single radiotherapy, chemotherapy, and immunotherapy for such osteosarcoma is poor, and the dysregulation of MYC amplification and immune-suppressive tumor microenvironment (TME) may be potential causes of anti-tumor failure." (PMID 39897587, 2025). "Additional samples from this patient during neoadjuvant chemotherapy and following resection of the primary tumor showed decreasing 5-hmC levels on MYC, consistent with decreased osteosarcoma derived cfDNA from a treated tumor and clinically decreased disease burden." (PMID 40951266, 2025). "Notably, polyamine supplementation can restore these tumorigenic features that were lost upon AZIN1 knockdown, underscoring the tight functional interplay between polyamines and MYC in osteosarcoma pathophysiology." (PMID 40246846, 2025). "Therefore, our results reveal a powerful strategy for targeted combination therapy of MYC-amplified osteosarcoma." (PMID 39897587, 2025). "In addition, MYC and NF-κB can also regulate each other’s target genes, forming a complex regulatory network to further promote the occurrence and development of osteosarcoma." (PMID 40786506, 2025). "Through the use of both two-dimensional and three-dimensional cell culture models, we have demonstrated that our drug delivery system, which is based on magnetic-driven hydrogel micro-robots, can effectively eradicate tumor cells and enhance the chemosensitivity of MYC-dependent osteosarcoma cells." (PMID 38638876, 2024). "Thus, the therapeutic targeting of the MYC/SE axis emerges as a promising avenue for the management of osteosarcoma patients." (PMID 38481812, 2024). "Our study will investigate the application value and research progress of magnetic-driven hydrogel micro-robots loaded with Ro-3306 in improving the chemotherapy sensitivity of MYC-dependent osteosarcoma, with the aim of improving the prognosis of MYC-driven osteosarcoma patients." (PMID 38638876, 2024). "Moreover, frequent amplification of the RUNX2 gene in osteosarcoma cell lines correlates with elevated RUNX2 levels, subsequently initiating MYC transcription and driving osteosarcoma tumorigenesis and progression." (PMID 38430423, 2024). "Consequently, our magnetic-driven hydrogel micro-robot drug delivery system shows promise for the treatment of MYC-dependent osteosarcoma." (PMID 38638876, 2024). "In osteosarcoma data, we found that 12 splicing factor genes were associated with multiple pathways in the Hallmark gene set, including the EF2, G2M, WNT, DNA repair, and MYC pathways." (PMID 39286028, 2024). "In addition, in the independent validation cohort, it was found that osteosarcoma patients with high MYC, P4HA1, and RAMP1 protein expression had worse RFS." (PMID 37055822, 2023).
osteosarcoma (continued). "Interestingly, one study found amplifications of the c-MYC gene in just 7% of adult cases of osteosarcoma, while another study reported a 40% frequency in childhood osteosarcoma compared with 5% in adults." (PMID 37894411, 2023). "Considering that upregulation or amplification of MYC is a common event in osteosarcoma, the high demand for cystine might be at least partially met by MLX-mediated cystine uptake." (PMID 37460542, 2023). "Additionally, other authors have reported the implication of aerobic glycolysis in osteosarcoma, particularly through c-MYC." (PMID 37796407, 2023). "We hypothesize that USP37 may be a potential contributor to poor prognosis in MYC-driven cancers such as osteosarcoma." (PMID 37118828, 2023). "It was reported that MYC was related to metastasis of patients with osteosarcoma." (PMID 36807122, 2023). "Therefore, the upregulated MYC TARGETS, E2F TARGETS, MTORC1 signaling, and WNT β-catenin signaling in high-risk group promoted metastasis of patients with osteosarcoma." (PMID 36807122, 2023). "Subsequent studies showed that the combination of thiram and HC further inhibited the proliferation and migration of osteosarcoma cells, increased apoptosis and cycle arrest, and further decreased the expression of beta-catenin, c-MYC, Cyclin-D1 and MMP7 compared with HC alone." (PMID 36978114, 2023). "Given the integral role of MYC in cancer metastasis in osteosarcoma, this result is expected." (PMID 35887382, 2022). "Additionally, the S1P/S1PR3 axis plays a role in promoting cancer cell proliferation and aerobic glycolysis as well as inhibition of apoptosis by activating the YAP/c-MYC/phosphoglycerate mutase 1 axis in osteosarcoma cells." (PMID 35625898, 2022). "Western blotting analysis revealed that the level of MYC was up-regulated in osteosarcoma." (PMID 36119478, 2022). "S1PR3 signaling promoted aerobic glycolysis by the YAP/c-MYC/PGAM1 axis in osteosarcoma." (PMID 36361531, 2022). "In this study, we found that MYC was highly expressed in osteosarcoma tissues and cell lines." (PMID 36586072, 2022). "Finally, we found that MYC knockdown or MBTPS2 overexpression inhibited osteosarcoma migration/invasion through affecting autophagy." (PMID 36586072, 2022). "Moreover, several molecular markers for osteosarcoma have also been discovered, including MYC, Cyclin E1, and MiR-455-3p, which are all considered to be promising therapeutic targets." (PMID 33858425, 2021). "MYC was demonstrated to be related to progression and poor prognosis in osteosarcoma." (PMID 34079579, 2021). "Therefore, targeting MYC/super-enhancer axis represents a promising treatment strategy for patients with osteosarcoma." (PMID 34079579, 2021). "Moreover, increased expression of c-MYC was proved to enhance the invasive ability of osteosarcoma cells by targeting MEK-ERK pathway." (PMID 34335109, 2021). "Overall, our data suggested that super enhancer inhibitors are promising small molecules that can target the MYC signaling in osteosarcoma and therefore could be used as therapeutic drug for the treatment of osteosarcoma patients." (PMID 29644114, 2018). "Taken together, these data imply that role of DGKZ in osteosarcoma pathogenesis may function via regulation of MYC signal pathway." (PMID 30662872, 2018). "Taken together, it could be concluded that DGKZ might exert an enhancing effect on activity of MYC signal pathway to impact on osteosarcoma proliferation." (PMID 30662872, 2018). "Additionally, microarray and IPA analyses demonstrated a alternation in expression of signaling-related genes in osteosarcoma cells and verified MYC pathway as a direct downstream target of DGKZ." (PMID 30662872, 2018). "It has also been shown in mice that c-MYC overexpression in mesenchymal bone stem cells may induce osteosarcomas." (PMID 28484590, 2017).
osteosarcoma (continued). "Similarly, the genetic inactivation of c-MYC in conditional mouse models of osteosarcoma, hepatocellular carcinoma and T-cell ALL triggered a global reduction in histone H4 acetylation and an increase in heterochromatic H3K9me3." (PMID 28505071, 2017). "In this context, other MYC gene family members may also be pivotal in the development of H3F3A mutant osteosarcomas." (PMID 28484590, 2017). "Seven (31.8%) of the radiation-induced osteosarcomas revealed c-MYC amplification." (PMID 24861215, 2014). "However, a regulatory network was recently described in osteosarcoma, demonstrating that miRNAs of the 14q32 locus act cooperatively to destabilize MYC and thus control the expression of the miR-17-92 cluster." (PMID 23133552, 2012). "The combination of these findings suggests that further study of the 8q24 locus may yield important insights into the regulation of MYC and its role in osteosarcoma pathogenesis." (PMID 21437228, 2011). "Additionally, overexpression of IFI16 protein in human osteosarcoma cell line Saos-2 down-regulated the expression of c-MYC and RAS genes." (PMID 20052289, 2010). "The finding that MYC gene amplification may be more common in pagetic than primary osteosarcoma warrants further study and suggests pathogenetic differences between primary osteosarcomas and those arising in the setting of Paget's disease." (PMID 18521214, 1997). "However, previous studies have shown that in certain subtypes of sarcomas (both BSs and STSs), such as Rhabdomyosarcoma, osteosarcoma, synovial sarcoma, Malignant Rhabdoid Tumor, Leiomyosarcoma, Ewing’s sarcoma, liposarcomas, and Atypical Teratoid/Rhabdoid tumor, MYC is frequently amplified." (PMID 40076599, 2025). "Therefore, combining magnetic-driven hydrogel micro-robots with CDK1 inhibition may be an effective method to improve the chemotherapy sensitivity of MYC-dependent osteosarcoma, and is expected to improve the prognosis of MYC-driven osteosarcoma patients." (PMID 38638876, 2024). "However, exactly how MYC influences the function of MLX in osteosarcoma remains unclear and needs to be explored." (PMID 37460542, 2023). "Moreover, the results of IHC demonstrated that MYC expression was up-regulated in the metastatic osteosarcoma patient, and MBTPS2 showed relatively high expression level in the non-metastasis patient, which suggested the relationship between autophagy and metastasis in osteosarcoma." (PMID 36586072, 2022). "Besides, MYC could be suppressed by super-enhancer inhibitors to effectively inhibit growth, migration, and invasion of osteosarcoma cells." (PMID 34079579, 2021). "Similarly, amplifications of MYC, BRCA2, and a co‐amplification of the region PDGFRA–KIT occurred mostly in recurring tumors (P1, P2, P4, P6, P7, P10), whereas JUN and APC mutations occurred in a single osteosarcoma primary (P1)." (PMID 33963544, 2021). "In a word, the MYC expression may act as a biomarker in osteosarcoma metastasis." (PMID 32974202, 2020). "In addition, the mis-regulated expression of oncogene MYC is often found in osteosarcoma patients." (PMID 32974202, 2020). "Thus, we speculated that DGKZ might regulate MYC signal pathway via possible interaction with ERK1/2 in carcinogenesis of osteosarcoma and utilization of DGKZ-ERK1/2-MYC interacting axis inhibitor might be an effective approach in treatment of osteosarcoma." (PMID 30662872, 2018). "Second, the MYC LOF target profile used in this study was derived from U2OS cells, an osteosarcoma line with unique transcriptional and epigenetic characteristics." (PMID 41025936, 2025). "qRT-PCR showed MYC, BNIP3, IGFBP5, and SPP1 substantially exhibited a trend of high expression in osteosarcoma cells." (PMID 41282023, 2025).
osteosarcoma (continued). "•TEM-responsive nanocomposite hydrogel was able to control MYC and ICD levels for the treatment of MYC-amplified osteosarcoma." (PMID 39897587, 2025). "Systematically cell mapping by scRNA-seq analysis revealed the stem-like population in chemotherapy-resistant osteosarcoma having stem cell marker CD117, MYC oncogene, epigenetic regulator JMJD3, and angiogenesis marker VEGFR2." (PMID 39359731, 2024). "The knockdown of MYC and P4HA1 significantly inhibited the proliferation, invasion and migration of osteosarcoma cells." (PMID 37055822, 2023). "Further correlation analysis found BNIP3 to have a significantly positive correlation with MYC, NELL1, SAR1A, PLOD2, and other genes proven to promote osteosarcoma metastasis." (PMID 37190333, 2023). "However, it is still largely unknown about the regulating mechanisms of MYC in osteosarcoma (OS)." (PMID 37151387, 2023). "MYC expression, a protein stabilized by USP37, is strongly related to many sarcomas, including osteosarcoma." (PMID 37118828, 2023). "Conclusively, we confirmed the correlation of MYC or MBTPS2 with autophagy and metastasis in osteosarcoma, which provides further verification of the validity of the model." (PMID 36586072, 2022). "MYC knockdown or MBTPS2 overexpression prevented the capacity of migration and invasion in osteosarcoma cell lines through inhibiting cellular autophagy." (PMID 36586072, 2022). "Since we were more interested in MYC and MBTPS2, we further verified their expression in osteosarcoma and their correlation with osteosarcoma metastasis in vitro." (PMID 36586072, 2022). "More importantly, we verified that autophagy-related genes, MYC and MBTPS2, were closely related to tumor cells metastasis in osteosarcoma." (PMID 36586072, 2022). "In particular, CNV was more frequent in CCND3, AURKB, CCNE1, GID4, and MYC in P-AYA, while MDM2, CDKN2A/B, and FRS2 were more frequently altered in adult osteosarcoma (p < 0.001)." (PMID 35705558, 2022). "MYC has been shown to maintain the stemness of CSC in a variety of tumors, and its role in osteosarcoma stem cells has also been revealed." (PMID 36059448, 2022). "Inhibition of MYC reprograms TME by recruiting T lymphocytes and activating the CD40/CD40L system in osteosarcoma." (PMID 36106335, 2022). "Collectively, these results demonstrated that MYC and MBTPS2 were involved in the metastasis of human osteosarcoma cells by affecting autophagy, which was consistent with our findings based on the public databases." (PMID 36586072, 2022). "Given the intricate connection between autophagy and metastasis, we next examined the effects of MYC silencing and MBTPS2 overexpression on metastasis ability of osteosarcoma cells by Transwell assay." (PMID 36586072, 2022). "In cell experiments, similar results were found that MYC and MBTPS2 were differentially expressed in hFOB and osteosarcoma cell lines at the mRNA and protein levels." (PMID 36586072, 2022). "From MSCs to osteosarcoma, CDKN2A, ALPL, SPARC (osteonectin) and MYC were considered as origin-related factors." (PMID 34828292, 2021). "Our results showed that compared with osteoblasts, AMBRA1 was down-regulated in U2OS and 143B, and while MYC and VEGFA were up-regulated in osteosarcoma cells." (PMID 34513835, 2021). "A risk score model constructed based on four epigenetic modification-related genes (MYC, TERT, EIF4E3, and RBM34) can effectively predict the prognosis of patients with osteosarcoma." (PMID 34853590, 2021). "Taken together, these data suggest that the proliferative effect of PAFAH1B3 in osteosarcoma is related to the regulation of the expression of EIF4EBP1, MYC, PTGS2 and RPS6KB1." (PMID 34136395, 2021).
osteosarcoma (continued). "These two groups of studies showed that MYC suppressed BMAL1 across a wide range of cancers, including osteosarcoma, neuroblastoma, hepatocellular carcinoma, Burkitt’s lymphoma, and T cell acute lymphoblastic leukemia." (PMID 34299381, 2021). "In osteosarcoma, NNT-AS1 can sponge miR-320a and up-regulate the expression of β-catenin, RUNX2, p-AKT, insulin-like growth factor type 1 receptor (IGF1R), MYC, cyclin D1, and MMP-13, thereby promoting osteosarcoma cell growth and tumor development." (PMID 33113895, 2020). "The integrated bioinformatics analysis was utilized to provide new insight into osteosarcoma development and metastasis and identified EGR1, CXCL10, MYC, and CXCR4 as potential biomarkers for prognosis of osteosarcoma." (PMID 32974202, 2020). "The results demonstrated that gene changes of CXCL10 (P = 0.044), GNAI1 (P = 0.048), MYC (P = 0.011), and OAS1 (P = 0.0091) were significantly correlated with the overall survival of osteosarcoma patients." (PMID 32974202, 2020). "In conclusion, our study demonstrated that DGKZ, a potential prognostic and predictive indicator in osteosarcoma, play a key role in proliferation of osteosarcoma, via its possible interaction with ERK1/2 and regulation of MYC pathway." (PMID 30662872, 2018). "Specifically, we used a supF reporter plasmid-based system containing the human c-MYC H-DNA-forming sequence in transfection experiments conducted in wild-type and siRNA-treated (DHX9-depleted) osteosarcoma U2OS cells." (PMID 24049074, 2013). "The role of the MYC oncogene has been extensively studied in osteosarcoma, and MYC amplification has been identified as a negative prognostic marker for survival." (PMID 41514647, 2025). "We used the CCLE database to examine the changes in the copy number and mRNA expression of the MYC gene in osteosarcoma cell lines, and selected SJSA, SAOS2, 143B, U2OS, and HOS - five types of human osteosarcoma cell lines - to detect MYC protein expression levels." (PMID 38638876, 2024). "U2OS osteosarcoma were similar to SHEP: in MYC-OFF, the strongest peak occurred at CT16, while no shared gene sets peaked at this time in MYC-ON." (PMID 37639465, 2023). "Interestingly, a recent study reported MYC activation strengthens chromatin interactions at super-enhancers and MYC binding sites in U2OS osteosarcoma cells." (PMID 36997534, 2023). "In a study of 56 osteosarcoma tissue samples not identified by age, the positive immunohistochemical expression of c-MYC was observed in 85.7% of samples." (PMID 37894411, 2023). "Through the R2 biologist web analysis with the established data set of “Mixed Osteosarcoma (Mesenchymal) -Kuijjer-127-vst-ilmnhwg6v2”, whose data source is GSE42352, we found that high expression of MYC was positively correlated with poor prognosis and enhanced metastasis in OS patients." (PMID 37151387, 2023). "Furthermore, RT-qPCR, Western Blotting and IHC results indicated that MYC and MBTPS2 were differently expressed in osteosarcoma tissues and cell lines." (PMID 36586072, 2022). "Our findings also suggested that MYC and MBTPS2 were two major factors regulating autophagy in osteosarcoma, and could serve as potential therapeutic targets for osteosarcoma." (PMID 36586072, 2022). "We reanalysed copy number readouts of 258 cases of high‐grade osteosarcoma from three different cohorts and identified a significant enrichment of focal MYC, but not CCNE1, amplifications in children." (PMID 33969640, 2021). "Our findings indicate that amplification of the MYC oncogene is a major driver of childhood osteosarcoma, while CCNE1 appears recurrently amplified independent of age." (PMID 33969640, 2021). "Furthermore, the proliferative effect of PAFAH1B3 in osteosarcoma was related to the regulation of the expression of EIF4EBP1, MYC, PTGS2 and RPS6KB1." (PMID 34136395, 2021).